AFP (alpha fetoprotein)
Diseases named in the same sentence as AFP in open-access papers (continued):
Sharing a sentence is not in itself a finding about the gene and the disease.
rickets (1 paper, 2022). Bone softening and weakening usually caused by deficiency or impaired metabolism of vitamin D. Deficiency of calcium, magnesium, or phosphorus may also cause rickets. "These children responded well to NTBC, with growth spurts, healing of rickets, disappearance of focal hepatic lesions and steep fall in alpha fetoprotein." (PMID 35536841, 2022).
schistosomiasis (1 paper, 2025). An infectious disease caused by parasitic trematodes of the genus Schistosoma that colonize human blood vessels and release eggs that can cause granulomatous reactions leading to acute (swimmer's itch or acute schistosomiasis syndrome) or chronic disease. "In our previous study, we used seven variables (Age, AST, DBil, ALP, HBsAg, AFP, Clinical classification) to predicted 2-years mortality in 2210 patients with advanced schistosomiasis, which was helpful for decision-making of clinicians to some extent." (PMID 40424464, 2025).
schizophrenia (1 paper, 2023). A major psychotic disorder characterized by abnormalities in the perception or expression of reality. "We transformed these proteins to their encoding gene IDs and identified the top 20 genes as the most probable schizophrenia-risk genes, including the EYA3, CNTN4, HSPA8, LRRK2, and AFP genes." (PMID 37966892, 2023).
Spastic paraplegia (1 paper, 2024). Complete loss of the ability to move the lower limbs accompanied by spasticity of the lower limbs. "In the first case, the presence of Alpha-Fetoprotein (AFP) levels below 15 μg/L can orient the diagnosis towards AOA1 rather than AOA2, while the occurrence of spastic paraplegia should suggest SPG7 above SCAR10, that furthermore typically shows low Coenzyme Q10 (CoQ10) values." (PMID 38436911, 2024).
sudden infant death syndrome (1 paper, 2009). Unexpected death in infancy which remains unexplained following autopsy, review of the medical history, and investigation of the death circumstances and death scene. "There is a direct association between second-trimester maternal serum alpha-fetoprotein levels and the risk of sudden infant death syndrome (SIDS), which may be mediated in part through impaired foetal growth and preterm birth." (PMID 21532726, 2009).
thymic large cell neuroendocrine carcinoma (1 paper, 2023). An aggressive, non-small cell, poorly differentiated thymic neuroendocrine carcinoma, characterized by the presence of a high mitotic rate and, almost always, necrosis. "Few cases of AFP-positive thymic large cell neuroendocrine carcinoma have been reported, with no known previous report of an AFP-positive thymic small cell carcinoma." (PMID 37721573, 2023).
thymic small cell carcinoma (1 paper, 2023). "In contrast, neither NUT, CD 30 nor CD 117 was positive, indicating that the tumor was not NUT carcinoma or germ cell carcinoma but rather AFP-positive thymic small cell carcinoma." (PMID 37721573, 2023).
trisomy 13 (1 paper, 2024). Trisomy 13 is a chromosomal anomaly caused by the presence of an extra chromosome 13 and is characterized by brain malformations (holoprosencephaly), facial dysmorphism, ocular anomalies, postaxial polydactyly, visceral malformations (cardiopathy) and severe psychomotor retardation. "In China, researchers have used proteomic techniques to identify many biomarkers for pregnancy-related pathological conditions, such as β-hCG for Down's syndrome and AFP for trisomy 13,18 syndrome, which were almost derived from or secreted by fetal, maternal circulation, and placental tissues." (PMID 38835013, 2024).
urachal adenocarcinomas (1 paper, 2022). "Other serum biomarkers described in low case numbers of urachal adenocarcinomas include lactate dehydrogenase (LDH), cancer antigen 15-3 (CA15-3), AFP and neuron-specific enolase (NSE)." (PMID 36010242, 2022).
urethral adenocarcinoma (1 paper, 2019). "We report an extremely rare case of an alpha-fetoprotein- (AFP-) producing female primary urethral adenocarcinoma with neuroendocrine differentiation (NED)." (PMID 31281709, 2019). "The tumor was finally diagnosed as an AFP-producing urethral adenocarcinoma with NED." (PMID 31281709, 2019).
tumor (5,877 papers, 1976 to 2026). "Overall, high levels of serum creatinine, largest tumor size, bilirubin, and AFP are strongly associated with increased mortality risk, while lower values of such variables correspond to a decreased risk." (PMID 41536859, 2026). "RDH16 expression was significantly reduced in HCC tissues compared with non-tumor liver tissues and was associated with vascular invasion, elevated alpha-fetoprotein levels, poor tumor differentiation, and advanced T stage." (PMID 41601632, 2026). "Multivariate analysis identified higher tumor burden, elevated AFP levels, TACE, and infiltrative HCC as independent risk factors for PFS in patients with intermediate-stage HCC." (PMID 41199230, 2025). "Chi-square (and Fisher’s exact) test demonstrated an association between DDX3X expression and elevated serum alpha-fetoprotein levels, larger tumor size as well as advanced TNM stage." (PMID 41198618, 2025). "Intriguingly, Eubacterium coprostanoligenes showed dual associations, positively with AFP (a tumor marker) and negatively with PT/INR, which support its complex role in coagulation and oncogenesis." (PMID 41030556, 2025). "Regarding associated conditions with AIS, we conducted tumor marker evaluations, including AFP, B-HCG, and CA-125, which were performed in our case." (PMID 39839690, 2025). "Clinically, AFP serves as a practical indicator for treatment efficacy, with lower levels associated with improved tumor response and survival outcomes." (PMID 40308490, 2025). "For example, integrating AFP with ctDNA mutations or epigenetic alterations can enhance the detection of early recurrence and provide insights into tumor evolution under therapeutic pressure." (PMID 40221793, 2025). "Some studies suggest that CTNNB1 mutations correlate with less aggressive tumor behavior, reduced invasiveness, lower serum alpha-fetoprotein (AFP) levels, and better-differentiated HCC." (PMID 40243493, 2025). "In this study, significantly high KLF5 expression in the HCC group was associated with TNM stage, tumor size, AFP level, portal vein thrombosis, HBV infection, and the 5-year survival rate of HCC patients." (PMID 40697993, 2025). "In the multivariate analysis, the largest tumor size >3 cm, >200 AFP levels, and NLR >5 were detected as preoperative risk factors for DFS rates." (PMID 40709064, 2025). "IRE1α was found to cleave consensus sequences on genes encoding tumor markers including AFP, PSA, CEA, TG, CA15‐3, and CA125." (PMID 40547943, 2025). "Through extensive calculations and statistical analyses, we identified ill‐defined pseudo capsules, non‐smooth tumor margins, the presence of peritumoral star nodes, and elevated AFP levels exceeding 400 ng/mL as major risk factors for high Ki‐67 expression." (PMID 39964132, 2025). "TNM staging, alpha-fetoprotein levels, tumor size, and risk score grouping were all substantially correlated with prognosis (p < 0.05), according to the univariate Cox analysis of the GSE14520 dataset." (PMID 40465746, 2025). "In the multivariate analysis, GGT >104 U/L, AFP >200 μg/L, largest tumor diameter >5 cm, and low MPV emerged as independent risk factors for worse TFS and OS." (PMID 40091304, 2025). "The elevated AFP level further supported the diagnosis, as extremely high AFP levels are associated with tumor burden and poor differentiation." (PMID 40656331, 2025). "Elevated AFP levels have been reported to increase the risk of tumor recurrence after transplantation, and various criteria have been proposed to evaluate transplant eligibility based on AFP levels." (PMID 40430002, 2025). "Metroticket 2.0 is a competing-risk model that incorporates AFP, tumour size, and number to estimate 5-year survival and HCC-related death, with a publicly available calculator." (PMID 41301037, 2025). "Subsequent postoperative monitoring revealed a normalization of AFP levels, suggesting a close association between AFP and the tumor." (PMID 40900781, 2025).
tumor (continued). "The traditionally recognized risk factors for HCC recurrence, such as AFP level and tumor size, have indeed been widely validated in various clinical studies." (PMID 40937437, 2025). "In the TCGA‐LIHC dataset, a high oncoScore was significantly associated with elevated serum alpha‐fetoprotein (AFP) levels and advanced tumour grade." (PMID 41383134, 2025). "Clinically, high DAP3 expression was strongly associated with larger tumor size and elevated AFP levels, demonstrating good diagnostic value according to ROC analysis." (PMID 40051634, 2025). "Tumor size and elevated AFP levels have previously been identified as risk factors for incomplete tumor ablation after HIFU treatment." (PMID 41458596, 2025). "Tumor-associated antigens such as AFP and glypican-3 (GPC-3), which are highly expressed in tumor cells, are often targeted in specific immunotherapy for HCC." (PMID 40432108, 2025). "Beyond its role in hepatic cell differentiation and regulation of key markers such as ALB and AFP, HNF4α is also important in attenuating cancer‐associated characteristics and suppressing tumor progression." (PMID 41244070, 2025). "Most engineered ACT targets in HCC fall into three categories: tumor-associated or tumor-specific antigens (AFP, GPC-3), viral-derived antigens (HBV, HCV), and cancer-testis antigens (NY-ESO-1, MAGE)." (PMID 41041128, 2025). "For the training set, univariable Cox regression analysis showed that AST, GGT, AFP, tumor size, tumor number, and DLR score were associated with RFS." (PMID 41428280, 2025). "Research suggests that CAR-T cells, targeting specific tumor-associated antigens such as AFP and GPC3, can be effective in enhancing T cell responses." (PMID 41514551, 2025). "Previous studies have shown that SPP1 expressing Tumor Associated Macrophages (TAMs) are primarily enriched in AFP positive HCC and are characterized by reduced phagocytic function but enhanced pro-angiogenic capacity, which aligns with our findings." (PMID 40474968, 2025). "Tumour antigens can be divided into tumour-associated foetal antigens (alpha-fetoprotein, CEA) and tumour-specific antigens, although in tumours affecting the human species no strictly specific antigenic structure has yet been highlighted." (PMID 39508984, 2025). "Using restricted cubic spline logistic regression, we investigated the association between the decline rates of AFP (Model 1), tumor size (Model 2), and 1-year recurrence." (PMID 40934000, 2025). "We found that substantial reductions in tumor size and AFP levels were significantly correlated with a lower risk of recurrence one year postoperatively." (PMID 40934000, 2025). "The RCS model showed that an AFP decline greater than 25% and tumor size reduction significantly lowered the risk of 1-year recurrence, but reductions in tumor size beyond 60% did not confer additional benefits in reducing recurrence risk." (PMID 40934000, 2025). "Our analysis indicates that complete responders do not have unique clinical characteristics, including demographics or established prognostic factors, such as disease cause, tumor differentiation, and AFP levels." (PMID 39998829, 2025). "Currently, in clinical practice, a tumor-specific marker, alpha-fetoprotein (AFP), is used for screening risk groups, disease progression, and survival prognosis." (PMID 40700271, 2025). "Abnormal β-catenin expression is associated with elevated serum alpha-fetoprotein (AFP) levels, poor tumor differentiation, and vascular invasion." (PMID 41388520, 2025). "We found that AFP and tumor size showed a statistically significant association in univariate Cox analysis." (PMID 40857604, 2025). "Csrp2 not only exhibits significantly higher expression levels in tumor tissues compared to normal tissues but also demonstrates superior diagnostic performance compared to AFP, a traditional biomarker for HCC." (PMID 41323394, 2025).
tumor (continued). "AFP elevation is commonly associated with poorly differentiated, aggressive tumors and has a positive correlation with tumor burden." (PMID 40762000, 2025). "Univariate and multivariate analyses showed that tumor size <6 cm, AFP <20 ng/mL and C-ion RT were associated with better LC." (PMID 40356208, 2025). "It is defined by elevated serum AFP (>20 ng/mL) or immunohistochemical evidence of AFP expression, and is associated with larger tumor size, frequent vascular and lymphatic invasion, and high liver metastasis rates (33%–72%)." (PMID 41550934, 2025). "The most robust predictors for survival in our study were underlying HCC cause, AFP, and tumor size." (PMID 39735678, 2025). "Based on well-defined tumour-associated antigens, peptide vaccines driven by AFP, GPC3 was well-tolerated and elicited high rate of spontaneous T cell responses." (PMID 40221793, 2025). "High PD-L1 expression, tumor mutational burden, gut microbiota composition, and early alpha-fetoprotein (AFP) reduction have been reported to be associated with a better response." (PMID 39941701, 2025). "Patients in the high-risk group exhibited advanced tumor staging and grading, elevated AFP levels, increased vascular invasion, and an unfavorable prognosis." (PMID 40269756, 2025). "In the multivariate analyses, the treatment group, age, tumor number, metastasis, and serum AFP level were independent risk factors for PFS, which was consistent with previous studies." (PMID 40486515, 2025). "The overexpression of IP-10 has been linked to serum AFP levels, tumor size and number along with TNM stage." (PMID 40373032, 2025). "The RETREAT score—comprising AFP at LT, MVI, and viable tumour burden—should be used to stratify 5-year recurrence risk (from less than 3% at score 0 to more than 75% at score ≥ 5) and to determine imaging and AFP surveillance cadence." (PMID 41301037, 2025). "Restricted cubic spline (RCS) logistic regression was used to identify thresholds for AFP decline and tumor size decline associated with 1-year recurrence." (PMID 40934000, 2025). "Low level of LINC02499 was associated with high AFP level, microvascular invasion, the number of satellite nodules, advanced tumor grade, and poor patient survival." (PMID 40596757, 2025). "Univariate Cox regression analysis indicated that several clinical and pathological factors held significant associations with OS, such as AFP levels, T-stage, N-stage, tumor size, and distant metastasis occurrence." (PMID 40485723, 2025). "Research indicates that elevated AFP is closely associated with advanced tumor stage, increased tumor size, lymph node involvement, and distant metastasis." (PMID 40485723, 2025). "AFP is a well-established and widely used tumor marker for HCC diagnosis and prognosis prediction associated with promoting HCC cell proliferation and vascular invasion." (PMID 40642170, 2025). "High AFP level (≥ 400 ng/mL) is associated with more aggressive tumor, higher risk of vascular invasion, higher rate of distant metastasis, and poor prognosis." (PMID 40221793, 2025). "A preoperative CTC count of ≥ 2 per 7.5 ml has been shown to predict tumour recurrence post-surgery, particularly in patients with a low risk of recurrence, such as those with serum AFP levels at or below 40 ng/mL." (PMID 40343687, 2025). "In the MC, PIVKA-II clearly outperformed AFP, highlighting the growing relevance of tumor biology markers in long-term risk assessment." (PMID 40656560, 2025). "Markers such as elevated AFP, large tumours, and multinodularity assist in risk stratification, but some patients remain poorly characterised." (PMID 40647548, 2025). "The results of the multivariate analysis indicated that several independent predictive factors were significantly associated with PFS, including ALB, AFP, tumor number, NLR, and PD-1 inhibitor treatment (HR=0.63; 95% CI: 0.46-0.86, P =0.004)." (PMID 40574845, 2025).
tumor (continued). "This patient's markedly elevated AFP level aligns with reports showing median AFP values between 20,000 and 100,000 ng/mL in paediatric cohorts, where higher levels are associated with a high tumour burden." (PMID 41583252, 2025). "This review demonstrates a direct association between elevated AFP levels and aggressive tumor phenotypes, highlighting its significant predictive value for clinical outcomes." (PMID 40430002, 2025). "In multivariate analysis, tumor size <6 cm, alpha-fetoprotein (AFP) <20 ng/mL and C-ion RT were independently associated with longer PFS." (PMID 40356208, 2025). "The prognosis for YST is significantly influenced by disease stage and elevated tumor markers, particularly AFP, which serves as both a diagnostic and monitoring marker." (PMID 40370888, 2025). "The Eubacterium coprostanoligenes group displayed a dual pattern: positively associated with AFP, a tumor marker, and negatively with PT/INR, a coagulation indicator." (PMID 41030556, 2025). "Global health status and QoL summary scores were inversely associated with tumor size and baseline AFP values." (PMID 40385925, 2025). "It has also been interpreted that increased AFP levels are associated with vascular invasion and loss of differentiation and are a good tool for predicting tumor behavior." (PMID 40709064, 2025). "While high AFP levels are linked with advanced disease and vascular invasion, its inability to detect recurrence early or capture tumor heterogeneity renders it suboptimal as a stand-alone tool." (PMID 40563578, 2025). "AFP levels are closely associated with tumor size, histological differentiation, and vascular invasion in HCC, making them useful for staging the disease." (PMID 40430002, 2025). "Multivariate analysis demonstrated that treatment with ATEZO/BEV, an AFP level ≥500 ng/dL, and tumor size were independently associated with OS." (PMID 41411278, 2025). "In conclusion, CMVr reduces the risk of tumor recurrence in patients with HCC undergoing LT, particularly among patients showing other well-known risk factors such as increased tumor burden, microvascular invasion, or increased AFP at transplant." (PMID 40557335, 2025). "OF these factors, high AFP, albumin levels, tumor diameter, high blood loss, high CNLC stage, high ALICE-CNLC stage, high BCLC stage, and high ALICE-BCLC stage were all found to be independently linked with RFS." (PMID 40052123, 2025). "A univariate Cox analysis based on PFS as clinical outcomes revealed that tumor size, lymph node-positive, clinical stage, venous invasion, nerve invasion, serum AFP, ARID1A mutation were prognostic factors for AFPGC (P < 0.05)." (PMID 39928247, 2025). "A preoperative model incorporating AFP, tumor burden, and LDLT was developed to predict the risk of MVI in post-LT specimens." (PMID 40361345, 2025). "We observed that the MDM2 methylation was associated with gender (p = 0.021), AFP (p = 0.011), number of tumors (p = 0.002), tumor size (p = 0.001), vascular invasion (p = 0.040) and TNM stage (p = 0.037)." (PMID 40432974, 2025). "Factors like poor tumor differentiation, vascular invasion, and high alpha-fetoprotein levels increase the recurrence risk." (PMID 40427147, 2025). "Despite advancements in diagnostic imaging, such as multiphase CT, MRI, and serum tumor markers like alpha-fetoprotein (AFP), early detection of LIHC remains challenging, with many cases being diagnosed at advanced stages." (PMID 41208994, 2025). "Correlation analysis between clinical variables and molecular clusters indicated that C1 was predominantly associated with advanced TNM stage, higher AFP, poor pathological grade, and larger tumor size, suggesting its more malignant characteristics." (PMID 41048998, 2025).